C22orf23 (chromosome 22 open reading frame 23)
Synonyms: FLJ32787; EVG1; LOC84645; dJ1039K5.6
Tractability: No criterion of Open Targets' tractability assessment is met for any kind of drug.
Gene: Protein-coding gene on chromosome 22 (37,943,050 to 37,953,669, reverse strand). Ensembl gene ENSG00000128346.
Subcellular location (Human Protein Atlas): Nucleoplasm
Gene Ontology:
Molecular function: protein binding
Genetic constraint (gnomAD): Loss-of-function variants: 22 observed, 25.44 expected, observed/expected ratio (o/e) 0.86, 90% interval 0.62 to 1.24. The upper end of that interval is the gene's LOEUF score, 1.24, which puts it in group 5 of 6, group 1 being the genes least tolerant of losing a copy. Missense variants: 204 observed, 248.45 expected, observed/expected ratio (o/e) 0.82, 90% interval 0.73 to 0.92. Synonymous variants: 78 observed, 87.99 expected, observed/expected ratio (o/e) 0.89, 90% interval 0.74 to 1.07.
Homologues: Orthologues: chimpanzee C22H22orf23 (99% identical), macaque C10H22orf23 (96% identical), pig C22orf23 (82% identical), mouse 1700088E04Rik (81% identical), rat C7h22orf23 (80% identical), rabbit C22orf23 (79% identical), guinea pig C22orf23 (74% identical), dog C22orf23 (69% identical), tropical clawed frog c4h22orf23 (50% identical), zebrafish si:dkey-43k4.3 (35% identical), Drosophila melanogaster CG5280 (27% identical).
Diseases named in the same sentence as C22orf23 in open-access papers:
C22orf23 is named in the same sentence as 1 disease in open-access papers, as found by Europe PMC text mining. Sharing a sentence is not in itself a finding about the gene and the disease.
C22orf23 shares sentences with these, for which no sentence is quoted: oligospermia (1 paper).